PTH (parathyroid hormone)
Diseases named in the same sentence as PTH in open-access papers (continued):
Sharing a sentence is not in itself a finding about the gene and the disease.
vitamin D deficiency (continued). "A high proportion of children with celiac disease in a region with increased insolation were found to have vitamin D deficiency, along with altered biochemical parameters, including increased parathyroid hormone and alkaline phosphatase levels and decreased total and ionized calcium and phosphorus." (PMID 40837675, 2025). "Early clinical observations linked vitamin D deficiency to aminoaciduria, attributing this effect to secondary hyperparathyroidism, a common consequence of low vitamin D, which results in elevated parathyroid hormone (PTH) levels." (PMID 41142409, 2025). "Animals with rickets and osteomalacia mainly caused by vitamin D deficiency had elevated PTH." (PMID 40231299, 2025). "The increased calcium demands during the formation phase may deplete calcium levels, stimulating the parathyroid hormone secretion, leading to secondary hyperparathyroidism, further accentuated by vitamin D deficiency caused by excessive bone utilization." (PMID 40981138, 2025). "The aim of our research was to evaluate and analyze serum 25(OH) vitamin D and parathyroid hormone (PTH) levels to investigate whether vitamin D deficiency serves as a risk factor for an increased incidence of acute respiratory infections (ARI) in children." (PMID 39585042, 2024). "Before attempting to reduce PTH, calcitriol levels should first be normalized through supplementation since Vitamin D deficiency could induce SHPT solely." (PMID 38785509, 2024). "In a trial to know the PTH response to vitamin D deficiency, we divided each group of vitamin D according to PTH level whether normal (14–65 pg/mL), low (< 14 pg/mL), or high (> 65 pg/mL)." (PMID 38982537, 2024). "Therefore, in vitamin D deficiency and in dietary calcium deficiency, PTH elevation and the development of secondary hyperparathyroidism is observed frequently." (PMID 39141058, 2024). "In addition, one-third of the patients included in this study who had vitamin D deficiency also had high PTH levels." (PMID 38674789, 2024). "The multiple logistic model showed that vitamin D deficiency is associated with an increased risk of dyslipidemia and uncontrolled hypertension (OR 2.2, 95% CI 1.1–4.8) when adjusted for age, obesity, parathyroid hormone levels, and cholecalciferol supplementation." (PMID 39439522, 2024). "In the multivariable model that adjusted sex, age, weight, blood pressure, HBA1C, T2DM duration, calcium, phosphorus, parathyroid hormone, lipids and renal function, vitamin D deficiency maintained its significant association with subclinical DPN (OR 1.276, 95% CI 1.086-1.501, P = 0.003)." (PMID 38590822, 2024). "Increases in the serum levels of FGF23 and PTH are responsible for vitamin D deficiency." (PMID 38541146, 2024). "The inverse correlation between vitamin D and PTH levels may be the expression of the effect of vitamin D deficiency on bone health, as an additional factor contributing to low bone mass and so to worsening of the disease." (PMID 37298368, 2023). "In postmenopausal women, vitamin D deficiency may increase the secretion of parathyroid hormone, which increases cortical bone porosity and fracture risk." (PMID 38089880, 2023). "Although ergocalciferol, cholecalciferol, and calcifediol supplementation effectively correct vitamin D deficiency or insufficiency, reduce parathyroid hormone (PTH), and improve calcium plasma levels, the effects of native sterols on BMD in KTRs remain undefined." (PMID 37189376, 2023). "PTH should have been high in the metabolic pathway due to vitamin D deficiency." (PMID 38813002, 2023). "Collectively, these results indicate that oxyphil differentiation in Def-Ts may be an indicator of metabolic stress and that vitamin D deficiency can induce gene expression changes that uncouple calcium sensing from PTH secretion." (PMID 36992820, 2023). "However, increased PTH with normocalcemia was presumably caused by vitamin D deficiency in our patient and it later normalized upon proper treatment." (PMID 37008936, 2023).
vitamin D deficiency (continued). "It is currently unknown whether intact PTH (iPTH) normalization is an appropriate target for both vitamin D deficiency repletion therapy and AVD and analogues treatment." (PMID 36678208, 2023). "Different vitamin D deficiency thresholds documented by studies may be explained by racial differences in PTH/25(OH)D relationship." (PMID 36721726, 2023). "Furthermore, regarding the calcium-PTH-vitamin D axis, vitamin D deficiency is a pivotal change in CKD-MBD, in which vitamin D receptors are expressed in the vascular endothelium." (PMID 35903313, 2022). "The elevated levels of PTH before bariatric surgery may be attributed to a vitamin D deficiency caused by NAFLD, which may be exacerbated by postbariatric surgery calcium absorption impairment." (PMID 35265372, 2022). "On the other hand, vitamin D deficiency stimulated PTH secretion." (PMID 35399923, 2022). "Vitamin D is essential for the homeostatic regulation of calcium, and reduced vitamin D intake can result in vitamin D deficiency or inadequate levels, impacting bone metabolism and leading to an increase in the secretion of parathyroid hormone (PTH) and subsequent increase in bone resorption." (PMID 35276834, 2022). "Additionally, higher PTH levels were associated with a greater risk of vitamin D deficiency (OR = 1.16, 95% C.I. [1.04–1.31], p = 0.016)." (PMID 36014846, 2022). "It has been previously proven that vitamin D deficiency may impair calcium metabolism and increase PTH concentration." (PMID 35514345, 2022). "Vitamin D deficiency can increase the level of PTH, which can increase the risk of cardiovascular diseases such as myocardial hypertrophy and valve calcification by influencing lipid metabolism and increasing inflammation, insulin resistance, hypertension and other mechanisms." (PMID 36230385, 2022). "Patients with a vitamin D deficiency had more often comorbidity (100% Vs 87.6%; p = 0.02), a significantly lower mean serum corrected calcium concentration (2.33 mmol/L Vs 2.37 mmol/L; p = 0.03) and higher mean serum PTH (6.4 pmol/L Vs 4.4 pmol/L; p < 0.001)." (PMID 35705746, 2022). "Moreover, higher PTH and vitamin D insufficiency can be jointly associated with higher HOMA-IR: the effect of PTH on insulin release from islets depends on vitamin D-related calcium and phosphorus." (PMID 36313112, 2022). "The relationship between vitamin D and blood pressure is regulated by PTH, and vitamin D deficiency may be a factor of hypertension onset; thus, it is necessary to study and understand this relationship and the regulatory mechanism between the two." (PMID 35814306, 2022). "Reduced IRS-1 and GLUT4 expressions will contribute towards lower insulin-induced glucose transport, and these could explain the link between vitamin D deficiency, high serum PTH levels, and insulin resistance." (PMID 35859985, 2022). "Vitamin D deficiency induced by hyperuricemia could cause secondary hyperparathyroidism, which leads to an increase in the PTH concentration." (PMID 36583002, 2022). "Since vitamin D deficiency stimulates PTH secretion, supplements could be prescribed in patients with low vitamin D levels, keeping in mind that they may worsen hypercalciuria in patients with Bartter syndrome." (PMID 35137195, 2022). "Treatment of secondary hyperparathyroidism in patients with CKD stages 3 or 4 and vitamin D deficiency should aim to control parathyroid hormone levels early in the disease course, while parathyroid cells are still responsive to physiological 1,25(OH)2D signalling." (PMID 34626363, 2022). "Apart from these, vitamin D deficiency could also lead to elevated levels of parathyroid hormone (PTH), which has been documented to reduce insulin-stimulated glucose uptake." (PMID 35859985, 2022). "On the other hand, vitamin D and PTH showed a moderate positive correlation only in patients, while in another casuistry, a negative correlation was observed, suggesting high PTH values in vitamin D deficiency and vice versa." (PMID 35919232, 2022).
vitamin D deficiency (continued). "Another mechanism that could explain the possible role of serum VDBP in developing DR is PTH imbalance due to vitamin D deficiency." (PMID 35778716, 2022). "Postoperative PTH levels in patients with severe vitamin D deficiency (16.5 ± 2.9 pg/mL) were significantly lower than those in patients with vitamin D deficiency (31.2 ± 4.7 pg/mL), vitamin D insufficiency (36.7 ± 4.5 pg/mL) and vitamin D sufficiency (36.9 ± 4.1 pg/mL)." (PMID 36550431, 2022). "Raised parathormone (PTH) and normal calcium concentrations can be observed both in normocalcemic primary hyperparathyroidism (nPHPT) and in secondary hyperparathyroidism, e.g. due to vitamin D deficiency." (PMID 36187131, 2022). "Additionally, parathyroid hormone (PTH) levels were found to be elevated due to vitamin D deficiency." (PMID 36014846, 2022). "Hence, vitamin D deficiency must be corrected to avoid an abnormal increase in bone resorption due to increased PTH secretion." (PMID 34429096, 2021). "Nevertheless, the mean concentration of 25(OH)D observed in our cohort corresponds to a moderate vitamin D deficiency and may increase the baseline PTH concentration and, consequently, modulate the effect of rhTSH on bone." (PMID 34768424, 2021). "Other well described factors involved in the process are: hyperphosphatemia, high parathyroid hormone (PTH) serum levels, vitamin D deficiency, elevated fibroblast growth factor 23 (FGF23) plasma levels, in addition to the presence of adenosylhomocysteine, hypervolemia, and anemia, among others." (PMID 34822562, 2021). "The study could be upgraded by simultaneous PTH determination to find out the cut-off values of vitamin D deficiency which might be different in different groups of risk children, to better define the need for treatment as well as the optimal vitamin D doses." (PMID 34599252, 2021). "The rational for supplying adequate amounts is that high serum PTH concentrations, even in patients with subclinical vitamin D deficiency, may contribute to bone fragility and falls in older adults." (PMID 33924215, 2021). "Based on the HR being 1.46 for the group with vitamin D deficiency alone and 0.88 for the group with PTH excess only, the excess relative risk (ERR) associated with deficient 25(OH)D levels was calculated as 1.46 − 1 = 0.46 and the ERR related to PTH excess was −0.12, separately." (PMID 34531372, 2021). "Therefore, this study determined the prevalence of a blunted PTH response among otherwise healthy young Saudi women with vitamin D deficiency and assessed its associated anthropometric and biochemical factors." (PMID 34580590, 2021). "In this study, vitamin D deficiency, increased PTH, and noninvasive liver biomarkers (Hyp, HA, FN, APRI, HypI, HAI, and FNI) could be a new trend of markers measuring malnutrition associated with liver severity in CHC-patients." (PMID 33884041, 2021). "This probably represents a behavioral change during pregnancy compared to before because of their vitamin D deficiency and could explain the observed higher PTH concentrations in these women." (PMID 33504033, 2021). "Widespread vitamin D deficiency among subjects in the GCC countries may also contribute to elevated plasma PTH levels of secondary hyperparathyroidism in XLH patients." (PMID 33660084, 2021). "Considering that most of our study subjects were elderly Chinese postmenopausal women with vitamin D insufficiency and normal PTH, there is a chance that suppressed PTH is associated with impaired glycemic metabolism and increased risk of diabetes in this type of population." (PMID 33833796, 2021). "It is interesting to note that in subjects with normal or mildly decreased renal function about 25% of subjects with vitamin D deficiency (25(OH)D<12 ng/mL) had PTH values above the upper limit of normal while in those with serum 25(OH)D over 30 ng/mL the percent drops to 8%." (PMID 33995282, 2021).
vitamin D deficiency (continued). "There is another study showing that vitamin D deficiency contributes to facilitating secondary hyperparathyroidism, while the increased levels of parathyroid hormone may accelerate the inflammatory response in atherosclerosis." (PMID 34745384, 2021). "HH patients in our study presented higher serum PTH, which could be explained by the state of vitamin D deficiency and, consequently, the synthesis of more parathyroid hormones by the parathyroid glands to maintain a stable serum calcium concentration." (PMID 34573286, 2021). "Furthermore, 54.4% of patients had serum PTH levels higher than the upper limit of normal, though serum calcium was within the normal range (n = 79), and 59.8% of patients had vitamin D deficiency (n = 82)." (PMID 34141703, 2021). "The secondary objective was to determine the association of serum concentrations of PTH with knee EOA and to determine the relationship between vitamin D deficiency, PTH level, and pain intensity, disability, psychological, and functional variables in patients with knee EOA." (PMID 34836290, 2021). "In some women, plasma/serum PTH concentrations increase during pregnancy, which may help to mobilize calcium and promote fetal growth in settings of dietary calcium deficits or vitamin D deficiency." (PMID 33640873, 2021). "It has been shown that vitamin D deficiency induces disturbances in PTH and calcium levels." (PMID 33800247, 2021). "A blunted PTH response to vitamin D deficiency is mainly observed among women with lower BMI." (PMID 34580590, 2021). "Furthermore, higher plasma TDF exposure was related to increased VDBP and lower 1,25(OH)D3, suggesting a functional vitamin D deficiency explaining TDF-associated higher parathyroid hormone levels." (PMID 34684572, 2021). "Thus, it seems that instead of vitamin D alone, concurrent vitamin D deficiency along with higher serum PTH levels was more closely linked to IR in obese women." (PMID 34950730, 2021). "Furthermore, women with elevated PTH and either low maternal dietary calcium intake and/or vitamin D deficiency had a higher risk of SGA and lower birth length and head circumference." (PMID 33640873, 2021). "In addition to vitamin D deficiency, an elevated PTH concentration is concerning as it is highly associated with cardio-metabolic diseases." (PMID 33396337, 2020). "In addition, participants with vitamin D deficiency had a significantly higher PTH concentration compared to those who were sufficient." (PMID 33260572, 2020). "Cholecalciferol also suppressed intact PTH only among patients with severe vitamin D deficiency." (PMID 32968158, 2020). "Therefore, the optimal serum concentration of 25(OH)D is defined as the concentration that suppresses the maximum release of PTH, being a measure of vitamin D deficiency and vitamin D toxicity." (PMID 32121398, 2020). "However, vitamin D deficiency (<20 ng/mL) during the first trimester of gestation was strongly associated with the odds of PTB amongst women with PTH levels above the 80th percentile (OR = 5.389, 95% CI (1.837, 15.812), p = 0.002)." (PMID 33114615, 2020). "Hypomagnesemia may cause a decrease in PTH secretion, while vitamin D deficiency is a risk factor for the development of PSHP." (PMID 34513060, 2020). "Mean PTH concentrations for Brazilian women with vitamin D deficiency (<25 nmol/L) were significantly higher compared to those with vitamin D insufficiency (25–49.9 nmol/L) (p < 0.01), vitamin D adequacy (50–74.9 nmol/L) (p < 0.01) and those with optimal vitamin D status (>75 nmol/L) (p < 0.001)." (PMID 32231092, 2020). "Notably, the prevalences of vitamin D deficiency and vitamin D deficiency plus elevated PTH (PTH>6.9 pmol/L) in this population were 72.5 and 40.2%, respectively (unpublished data)." (PMID 31914999, 2020).
vitamin D deficiency (continued). "And since the Lebanese population is at a high risk for vitamin D deficiency, prolonged secondary hyperparathyroidism may lead to higher PTH values in our population even after vitamin D repletion." (PMID 32148490, 2020). "Because vitamin D deficiency stimulates parathyroid hyperplasia and is associated with larger parathyroid adenomas and higher levels of PTH before and after surgery for PHPT, one could speculate that the IOPTH decline is slower in vitamin D deficient patients." (PMID 32256573, 2020). "In addition, vitamin D deficiency causes the body to store more fat by increasing parathyroid hormone levels." (PMID 33014983, 2020). "Furthermore, a regression analysis with smoothed spline curve fitting showed a biphasic correlation between eGFR and serum intact PTH concentration only in those participants with vitamin D deficiency." (PMID 32582730, 2020). "This extent of skeletal disease may partly be attributed to coexisting vitamin D deficiency as long standing Vitamin D deficiency can further exaggerate the secretion of PTH." (PMID 32968380, 2020). "This study of nearly 17 646 25(OH)D and 5579 PTH test results represent the largest aggregation of data used to illustrate the 25(OH)D status, the prevalence of vitamin D deficiency and the correlation between serum concentrations of 25(OH)D and PTH in a Southeast China population." (PMID 32415728, 2020). "In fact, calcium level regulation in patients with vitamin D deficiency depends on PTH levels." (PMID 33101410, 2020). "Because PTH may be increased in patients with vitamin D deficiency and decreased in vitamin-D-replete subjects, exclusion of patients with vitamin D insufficiency from the reference population for PTH values is mandatory." (PMID 32148490, 2020). "Preterm birth was associated with vitamin D deficiency in the multivariable model, being this association stronger amongst women with parathyroid hormone serum levels above the 80th percentile (adjusted odds ratio (aOR) = 6.587, 95% CI (2.049, 21.176), p = 0.002)." (PMID 33114615, 2020). "Thus, it seems that when eGFR is <60 mL/min/1.73 m2, a reduction in eGFR substantially increases serum intact PTH concentration only in the presence of vitamin D deficiency in the general population." (PMID 32582730, 2020). "Laboratory data further revealed severe vitamin D deficiency with subsequently increased levels of parathyroid hormone and osteocalcin, and deficiency in vitamin K reflected by low levels of clotting factors II, VII, IX and X, predisposing to bruising and hemorrhage." (PMID 32468113, 2020). "Vitamin D deficiency can activate the parathyroid to induce the release of parathyroid hormone, which was thought to increase serum uric acid level, and low vitamin D status may also be associated with risk of CVD." (PMID 33330592, 2020). "Furthermore, several authors have described the concept of functional vitamin D deficiency characterized by secondary hyperparathyroidism, which refers to elevated levels of PTH in combination with low levels of vitamin D." (PMID 33114615, 2020). "The significantly higher PTH concentration in this group may also be attributed to the concurrent presence of both secondary hyperparathyroidism induced by vitamin D deficiency as well as PHP." (PMID 33210066, 2020). "The Institute of Medicine (IoM) defines vitamin D deficiency as a concentration of 25(OH)D < 30 nmol/L, and vitamin D adequacy as a concentration of >50 nmol/L for all age groups based on integrating data from several health outcomes and PTH." (PMID 32916847, 2020). "A diagnosis of normocalcemic primary hyperparathyroidism can be made when the subject presents consistently elevated PTH concentrations in presence of normal calcium levels, after the exclusion of any cause of secondary PTH elevation (renal diseases, vitamin D insufficiency, etc)." (PMID 32148482, 2020).